ZDHHC22 (zDHHC palmitoyltransferase 22)
Description:
Palmitoyltransferase that could catalyze the addition of palmitate onto various protein substrates and be involved in a variety of cellular processes. Catalyzes the palmitoylation of KCNMA1, regulating localization of KCNMA1 to the plasma membrane. Might also mediate palmitoylation of CNN3 (By similarity).
Synonyms: C14orf59
Tractability: Antibody: its Gene Ontology location is reachable by antibodies, with high confidence; UniProt predicts a signal peptide or a membrane-spanning region; the Human Protein Atlas places it where antibodies can reach.
Gene: Protein-coding gene on chromosome 14 (77,131,270 to 77,143,032, reverse strand). Ensembl gene ENSG00000177108.
Subcellular location: Endoplasmic reticulum membrane; Golgi apparatus membrane
Subcellular location (Human Protein Atlas): Plasma membrane
Gene Ontology:
Molecular function: protein binding; protein-cysteine S-palmitoyltransferase activity; palmitoyltransferase activity
Biological process: protein localization to plasma membrane; protein palmitoylation; protein targeting to membrane
Cellular component: endoplasmic reticulum; endoplasmic reticulum membrane; Golgi apparatus; Golgi membrane; plasma membrane
Genetic constraint (gnomAD): Loss-of-function variants: 13 observed, 15.75 expected, observed/expected ratio (o/e) 0.83, 90% interval 0.54 to 1.31. The upper end of that interval is the gene's LOEUF score, 1.31, which puts it in group 5 of 6, group 1 being the genes least tolerant of losing a copy. Missense variants: 319 observed, 321.85 expected, observed/expected ratio (o/e) 0.99, 90% interval 0.9 to 1.09. Synonymous variants: 138 observed, 142.9 expected, observed/expected ratio (o/e) 0.97, 90% interval 0.84 to 1.11.
Homologues: Orthologues: chimpanzee ZDHHC22 (100% identical), macaque ZDHHC22 (99% identical), pig ZDHHC22 (96% identical), guinea pig ZDHHC22 (95% identical), rabbit ZDHHC22 (94% identical), rat Zdhhc22 (93% identical), mouse Zdhhc22 (92% identical), dog ZDHHC22 (91% identical), zebrafish zdhhc22 (46% identical), tropical clawed frog zdhhc22 (45% identical), Drosophila melanogaster CG18810 (24% identical), Caenorhabditis elegans dhhc-9 (17% identical), and 2 more. Paralogues in human: ZDHHC14 (23% identical), ZDHHC9 (21% identical), ZDHHC1 (20% identical), ZDHHC15 (20% identical), ZDHHC18 (20% identical), ZDHHC3 (19% identical), ZDHHC7 (18% identical), ZDHHC12 (18% identical), ZDHHC2 (18% identical), ZDHHC20 (18% identical), ZDHHC6 (18% identical), ZDHHC11B (17% identical), and 5 more.
Diseases named in the same sentence as ZDHHC22 in open-access papers:
ZDHHC22 is named in the same sentence as 10 diseases in open-access papers, as found by Europe PMC text mining. Sharing a sentence is not in itself a finding about the gene and the disease. The quoted sentences say what the papers report.
breast carcinoma (4 papers, 2022 to 2024). "Hypermethylation of the promoter CpG island of the ZDHHC22 gene is associated with poorer prognosis in breast cancer." (PMID 38279330, 2024). "The TUNEL staining of the primary tumors showed that the proportion of apoptotic breast cancer cells was increased after ZDHHC22 overexpression." (PMID 35541896, 2022). "Overexpression of ZDHHC22 inhibits breast cancer cell growth both in vitro and in vivo." (PMID 38279330, 2024). "IHC staining revealed that tumors in the ZDHHC22 group had a lower percentage of Ki-67 positive cells and mTOR expression than tumors in the other two groups, indicating ectopic ZDHHC22 expression suppressed the proliferation and expression of mTOR protein of breast cancer." (PMID 35541896, 2022). "The ZDHHC22 (abbreviated as ZDC22 in the Figures) expression was decreased in HER2-enriched and basal-like breast carcinoma, which had been verified as "more aggressive" subtypes, compared with luminal-like subtypes." (PMID 35541896, 2022). "We found ZDHHC22 expression was significantly lower in estrogen receptor (ER) negative breast cancer (BrCa) tissues and cell lines, and its expression was positively corelated with the clinical prognosis of BrCa patients." (PMID 35541896, 2022).
tumor (3 papers, 2022 to 2025). "There are only a few reports on the function of ZDHHC22 in tumor development and progression, and the results are discordant." (PMID 36982858, 2023). "These tumor-inhibiting effects are depending ZDHHC22 palmitoylation." (PMID 35541896, 2022). "Thus, we hypothesized that ZDHHC22 overexpression might suppress tumor growth by reducing the activation of the AKT pathway." (PMID 35541896, 2022). "The last gene of interest, ZDHHC22 (Zinc Finger DHHC-Type Palmitoyltransferase 22), is responsible for regulating large conductance calcium-activated potassium channels and, interestingly, is related to tumor progression and the immune microenvironment." (PMID 40428335, 2025).
cancer (1 paper, 2022). A tumor composed of atypical neoplastic, often pleomorphic cells that invade other tissues. "However, to the best of our knowledge, few studies have reported the pathological functions of ZDHHC22 in cancers." (PMID 35541896, 2022). "ZDHHC22, as a well-known member of palmitoyltrans-ferase family, its role has not been revealed in cancer." (PMID 35541896, 2022).
ZDHHC22 also shares sentences with these, for which no sentence is quoted: astrocytoma (1 paper); bladder cancer (1); cervical cancer (1); colorectal cancer (1); glioblastoma (1); infection (1); liver cancer (1).